INS (insulin)
Diseases named in the same sentence as INS in open-access papers (continued):
Sharing a sentence is not in itself a finding about the gene and the disease.
diabetes (continued). "Infusion of insulin at 5 mUnits/min over a 60 minute period lead to a significant increase in FBF in healthy controls from 3.4±0.4 to 5.0±0.7 mL.min−1.100 mL−1 (p<0.001), whilst in diabetics there was a small although non-significant rise from 2.7±0.5 to 3.6±0.6 mL.min−1.100 mL−1 (p = ns)." (PMID 23658699, 2013). "Using 8-month old db/db mice with diabetes for at least 22 weeks, the goal of this study was to investigate the relationship between induction of PGC-1α on cardiac inflammation and mitochondrial protein expressions in the absence of changes in blood glucose or insulin." (PMID 23936397, 2013). "When insulin expression was abrogated in the thymus using a knockout of Ins2 gene specifically in the AIRE (autoimmune regulator) expressing medullary thymic epithelial cells of mice, without affecting its expression in the beta-cells, diabetes developed in three weeks of age independent of sex." (PMID 24285974, 2013). "Therefore, in this study we performed joint tests of association between SNPs and CNVs at the genome-wide level with fasting insulin and HOMA-IR in 1,040 African American participants without diabetes in the Hypertension Genetic Epidemiology Network (HyperGEN) study." (PMID 21901158, 2011). "Patients with a history of insulin-treated diabetes were older (66 (range 55 to 75) versus 64 (49 to 74) years, P < 0.01) and more severely ill on admission, as reflected by the higher SAPS II and SOFA scores, than were patients without a history of insulin-treated diabetes." (PMID 20132545, 2010). "There is a possibility that in the beginning stages of STZ-induced diabetes, hepatic trans-sulfuration and re-methylation of the enzymes cystathionine β-synthase and cystathionine γ-lyase may increase in STZ-induced diabetic animals due to lack of insulin." (PMID 18036220, 2007). "Since our participants were young adults free of diabetes mellitus and some covariates in the adjusted models, such as TG and HDL-C, had a high correlation with the insulin resistance indices, the effect of lacking hemoglobin A1c or insulin adjustment at baseline might be minimized." (PMID 39806968, 2025). "Additionally, the glucose tolerance test and insulin tolerance test were not performed over the course of the in vivo experiment; thus, we could not clearly demonstrate that the animals in HFD groups developed insulin resistance or diabetes." (PMID 41374066, 2025). "However, lack of insulin or duration of hyperglycemia and resulting metabolic consequences of diabetes may also contribute to the observed severity of PAD among individuals with diabetes." (PMID 37139134, 2023). "Diabetes mellitus (DM) is a chronic non-communicable disease that occurs when the endocrine pancreas is not able to secrete suitable amount of insulin, or when the body does not respond to the insulin it produces." (PMID 36062030, 2023). "Interestingly, in a previous diabetic animal model, insulin was effective in restoring BD1 expression in the rat kidney; however, the low expression of BD1 due to diabetes could not be restored after insulin treatment in either the lung or brain of the same rats." (PMID 36982317, 2023). "However, PHZ, an SGLT1/2 inhibitor, which ameliorates hyperglycemia without enhancing insulin secretion or action, fails to suppress HCC in STAM mice, suggesting that amelioration of hyperglycemia per se is insufficient to protect from HCC in STAM mice and in patients with diabetes and NASH." (PMID 37852976, 2023). "However, a few suboptimal adherents stated that they lacked the necessary knowledge to count CHO content, adjust insulin dose accordingly, and base decisions on BGM results (Quote #13), and a couple others reported lacking a certain level of knowledge about long-term complications of diabetes." (PMID 38515508, 2022).
diabetes (continued). "Moreover, most β-blockers are not recommended as first-line treatment in patients with diabetes because of their negative cardiometabolic effects: increasing triglyceride level, decreasing HDL cholesterol level, hiding symptoms of hypoglycaemia and impairing insulin sensitivity." (PMID 35742943, 2022). "However, clinically relevant subgroups of people with diabetes, or specific therapeutic interventions, were not identified using the AGP because of the lack of important context variables, such as timing of meals, exercise and medication intake/insulin injection." (PMID 35380233, 2022). "It is designed to be used with any insulin delivery system and to permit comparisons of various systems (e.g., pen versus syringe, one pump versus another pump etc.)An instrument like the IDSRQ is not available in Brazil and might be useful to improve diabetes care." (PMID 34033280, 2021). "Chronic hyperglycemia may arise from a lack of insulin production (type 1 diabetes mellitus, T1DM) or to an exaggerated resistance to the cellular effects of insulin, accompanied by a decline in insulin production (type 2 diabetes mellitus, T2DM; the most frequent form)." (PMID 34572148, 2021). "The treatment with exogenous insulin in type-1 diabetic patients may be responsible for the non-significant difference in the rate of RSSC accumulation between the two groups (although according to the HbA1c data, diabetes was not well controlled in the majority of the individuals)." (PMID 28827705, 2017). "However, insulin did not restore the circadian rhythm in Clock (factorial design ANOVA, P > 0.05) and Bmal1 (factorial design ANOVA, P > 0.05), with the analysis showing statistically significant differences between the insulin-treated diabetes and control groups." (PMID 27611469, 2016). "Interestingly, subcutaneous transplantation of embryonic BAT can ameliorate STZ-induced diabetes, suggesting that BAT may play a key role in the regulation of glucose metabolism brought on by leptin in the absence of insulin." (PMID 25870537, 2015). "B420 had no additional benefit on plasma insulin compared to metformin only, but B420 significantly attenuated the glucose response in IPGTT and decreased fasting plasma glucose concentration, suggesting that a combination treatment could be more effective in treating diabetes than metformin alone." (PMID 26366205, 2015). "Pre-diabetes and T2DM are states of both insulin resistance and impaired insulin secretion, resulting in abnormal glucose regulation; hence, the increased incidence of poor skeletal health reported in those individuals may not reflect the independent actions of insulin on bone." (PMID 25258705, 2013). "While the mainstream treatment for diabetes currently relies on insulin replacement and hypoglycemic drugs, a paradigm unlikely to change in the immediate or distant future, the application of FMT introduces new perspectives and directions for the treatment of DM." (PMID 38660489, 2024). "DM is divided into two types, namely, type 1 diabetes mellitus (T1DM), which involves the destruction of beta cells in the islets, leading to an absolute lack of insulin secretion, and type 2 diabetes mellitus (T2DM), which involves an insufficient insulin secretion or combined insulin resistance." (PMID 35844498, 2022).
Insulin resistance (24,760 papers, 1998 to 2026). Increased resistance towards insulin, that is, diminished effectiveness of insulin in reducing blood glucose levels. "Its pathophysiology involves peripheral insulin resistance, dysregulated hepatic glucose production, and progressive β-cell dysfunction, ultimately leading to β-cell destruction and the consequent loss of insulin secretory capacity." (PMID 41599356, 2026). "Diabetes mellitus is characterized by chronic hyperglycemia resulting from insulin resistance and defects in insulin secretion and/or action caused by islet β-cell failure." (PMID 41521729, 2026). "Individuals with obesity-associated peripheral insulin resistance, on the other hand, showed disrupted central insulin action, along with a higher preference for palatable foods." (PMID 41495379, 2026). "Four clusters were identified: Liver Sensitive (LS), Pancreas Glucose Sensitive (PGS), Insulin Deficient (ID), and Insulin Resistant (IR), each with distinct dysglycemia risk." (PMID 41133433, 2026). "Obesity associated insulin resistance, however, reduces the ability of central insulin to influence mesolimbic activity." (PMID 41495379, 2026). "Correlation analyses showed that Shh levels were associated with insulin resistance in both sexes but reflected different disease states with early compensatory insulin secretion in males and late β-cell dysfunction in females." (PMID 41854531, 2026). "This case underscores the importance of regular review of automated insulin delivery data and consideration of endocrine causes of insulin resistance and increased insulin requirements in those with type 1 diabetes." (PMID 42221400, 2026). "Protein-protein interaction (PPI) analysis prioritized 25 hub genes, whose enrichment profiles implicated insulin resistance/insulin signaling and adrenergic signaling in cardiomyocytes." (PMID 42074126, 2026). "Briefly, intervention studies have shown that lower serum insulin and C-peptide levels are associated with improved insulin plasma clearance and less insulin resistance." (PMID 41546786, 2026). "Cortisol is associated with insulin resistance because it decreases insulin sensitivity in the liver and in the extra-liver compartment." (PMID 41536580, 2026). "For instance, low risk (LR or cluster 2), high risk low beta cell function (HR-LowBeta or cluster 3), high risk high insulin resistance (HR-InsRes or cluster 5), high risk high insulin secretion (HR-InsSecr or cluster 6)." (PMID 41547928, 2026). "Conversely, treatment with AYN and metformin resulted in a significant reduction in insulin concentrations, indicating that AYN effectively mitigated the excessive insulin secretion associated with insulin resistance." (PMID 41509193, 2026). "The pathogenesis of PCOS is closely associated with marked insulin resistance, whereas insulin secretion is usually preserved or even compensatorily elevated." (PMID 41573199, 2025). "In a recent study, it was found that the removal of epididymal white adipose tissue (EWAT) caused a significant positive impact on insulin resistance, serum insulin, hepatosteatosis, inflammation, and oxidative stress." (PMID 39858439, 2025). "One well-known pro-inflammatory cytokine is TNFα, which has been highly associated with obesity and T2D given its implications for insulin signaling and insulin resistance development." (PMID 40723425, 2025). "It is classified into two main types: type 1, which is caused by impaired insulin secretion, and type 2, which is mainly associated with the inability of cells to respond to insulin (i.e., insulin resistance)." (PMID 40573309, 2025). "One recent study found that the TM6SF2 genotype associated with red/processed meat intake, and another found that the GCKR genotype associated with insulin/insulin resistance and TGs to multiplicatively increase hepatic steatosis." (PMID 40166930, 2025).
Insulin resistance (continued). "Elevated serum free fatty acids (FFAs), caused by excessive lipolysis under systemic insulin resistance, result in ectopic fat deposition in skeletal muscle cells, disrupting insulin’s anabolic effects on muscle protein turnover." (PMID 41283458, 2025). "Consistent with our findings, there is evidence that females are generally more insulin-sensitive than males, and women have decreased susceptibility to fatty acid–induced peripheral insulin resistance." (PMID 41255977, 2025). "Insulin resistance is another key cause of infertility in obese women, a disease in which the body’s cells become less receptive to insulin, resulting in hyperinsulinemia (high circulating insulin)." (PMID 40430186, 2025). "Given that insulin resistance and hyperglycaemia are established risk factors for the development of diabetic retinopathy and possibly glaucoma, this improvement in insulin sensitivity is noteworthy." (PMID 40509955, 2025). "PTH has also been found to be inversely related to insulin sensitivity and higher levels are associated with insulin resistance and higher T2D prevalence." (PMID 39712337, 2025). "Insulin resistance, a state of impaired cellular response to insulin, is closely associated with oxidative stress and inflammation, often culminating in apoptosis." (PMID 40729004, 2025). "This dual pathway—genetic predisposition decreasing insulin secretion, and metabolic dysfunction increasing insulin resistance—underscores the importance of individualized approaches to preventing T2D." (PMID 39902403, 2025). "T2DM is characterized by hyperglycemia resulting from the combination of impaired regulation of glucose metabolism by insulin, known as insulin resistance (IR), and reduced insulin secretion caused by pancreatic islet β-cell dysfunction." (PMID 39861118, 2025). "Type 2 diabetes mellitus (T2DM) is caused by insufficient insulin and peripheral insulin resistance, resulting in hyperglycemia." (PMID 40006017, 2025). "What’s more, obesity is directly associated with insulin resistance, which stimulates compensatory insulin secretion, leading to hyperinsulinemia." (PMID 40678066, 2025). "Caveolin-1 is essential for improving insulin sensitivity, and studies have shown that Cav-1-deficient mice exhibit insulin resistance and defective insulin receptor protein expression." (PMID 41280311, 2025). "Phosphorylation will cause degradation and insulin sensitivity reduction, ultimately contributing to the development of insulin resistance (IR)." (PMID 39858445, 2025). "Evidence suggests that insulin resistance is associated with endothelial dysfunction, possibly through the impairment of insulin‐related signaling pathways." (PMID 39123295, 2025). "Research shows that brain insulin resistance, or the disruption of insulin signaling in the brain, is linked to cognitive decline and Alzheimer’s disease (AD), making it a risk factor for sporadic AD development." (PMID 39948335, 2025). "Inflammatory and oxidative responses induced by PM2.5 impair insulin sensitivity and promote insulin resistance, thereby elevating the risk of type 2 diabetes—a process that accelerates atherogenesis and worsens cardiac outcomes." (PMID 41210342, 2025). "Mice with whole body deficiency of Esr1 develop insulin resistance, suggesting a protective role of Esr1 in insulin sensitivity." (PMID 40666843, 2025). "A higher fiber intake in women with PCOS is associated with better insulin sensitivity and is inversely correlated with the homeostatic model assessment of insulin resistance (HOMA-IR) and abdominal fat." (PMID 40733002, 2025). "IRS1 and AKT play a key role in the insulin signaling pathway, and their downregulation is associated with insulin resistance." (PMID 40431415, 2025). "Chronic insulin resistance along with a compensatory increase in insulin release is a hallmark of obesity, type 2 diabetes (T2D), and metabolic dysfunction–associated steatotic liver disease (MASLD)." (PMID 39998445, 2025).
Insulin resistance (continued). "Two recent studies in children and adults demonstrated that greater insulin resistance or higher insulin levels after an oral glucose load were associated with lower levels of BAs." (PMID 41306439, 2025). "A genetic study showed that DGKB involved loci associated with insulin secretion and processing, potentially leading to insulin resistance, and further connected to T2D." (PMID 41393296, 2025). "Chronic suppression of S6K1 activity has been shown to disrupt insulin signaling cascades, culminating in impaired glucose uptake and pancreatic β-cell dysfunction, which predispose to insulin resistance and type 2 diabetes mellitus." (PMID 40649702, 2025). "Holstein cows, known for their genetic predisposition to insulin resistance due to high milk production, often have altered ovarian follicular dynamics after calving, with reduced concentrations of insulin and IGF-1." (PMID 40725447, 2025). "These processes contribute to the development of low-grade chronic inflammation in peripheral tissues, which is closely associated with insulin resistance and reduced insulin sensitivity." (PMID 40698248, 2025). "Insulin resistance, characterized by diminished sensitivity to insulin’s metabolic actions, is mediated by genetic predisposition and environmental determinants." (PMID 41036194, 2025). "Hyperinsulinemia associated with type 2 diabetes leads to decreased insulin signaling in the brain; thus, the brain in AD is in a state of insulin resistance, and AD has been referred to as “type 3 diabetes”." (PMID 40283962, 2025). "The underlying mechanism involves adipose tissue insulin resistance and diminished suppression of insulin-dependent lipolysis." (PMID 41198895, 2025). "These modifications have been linked to impaired insulin secretion and increased insulin resistance, impaired glucose metabolism, and inflammation." (PMID 41295241, 2025). "These metabolic and hormonal differences can modify pancreatic β-cell and insulin-sensitive tissue susceptibility to MeHg-induced oxidative stress and mitochondrial dysfunction, potentially yielding sex-specific risks for insulin resistance and T2D." (PMID 41009549, 2025). "In patients with PCOS, elevated blood glucose levels trigger a compensatory increase in insulin secretion due to underlying insulin resistance." (PMID 40776915, 2025). "Insulin resistance, a condition in which the body’s cells become less receptive to the hormone insulin, can be caused by ROS." (PMID 40168333, 2025). "The quantitative insulin sensitivity check index (QUICKI) is a clinical indicator for estimating insulin sensitivity and assessing insulin resistance in T2DM patients or those at risk, calculated using fasting blood glucose and insulin levels." (PMID 40507062, 2025). "While insulin resistance is a hallmark of the disease, it is insufficient insulin secretion from the beta cell that ultimately drives the transition to hyperglycaemia." (PMID 40768044, 2025). "The expansion of adipose tissue is strongly associated with insulin resistance, a metabolic disorder in which the body’s cells exhibit reduced responsiveness to normal insulin levels, leading to compensatory hyperinsulinemia." (PMID 40214973, 2025). "Increased insulin resistance often results in elevated ceramide levels, which have been associated with impaired insulin signaling and metabolic dysfunction." (PMID 40700071, 2025). "In obese and insulin-resistant individuals, elevated levels of ceramides can directly cause cellular insulin resistance by inhibiting downstream effects of insulin signaling, such as GLUT4 translocation." (PMID 40429815, 2025). "The premise underpinning this negative association is that the fat‐free mass index (FFMI) which is FFM indexed to height (FFM/Ht2) is positively associated with impaired insulin sensitivity or insulin resistance." (PMID 39895188, 2025).